IFNG (interferon gamma)
Diseases named in the same sentence as IFNG in open-access papers (continued):
Sharing a sentence is not in itself a finding about the gene and the disease.
tumor (continued). "IFNγ is released by immune cells in the tumor microenvironment and tumor cells respond by activation of JAK-STAT signaling, leading to IRF1 activation." (PMID 39237877, 2024). "Altogether, these results emphasized the importance of the transition from a TGFβ- to an IFNγ-dominated tumor microenvironment, which shuts down multiple pathways through which TGFβ and CCKAR signaling limit collagen expression." (PMID 39574893, 2024). "In the B16-huCD19 tumor model, significantly more IL-18 and IL-23, as well as a trend towards more IL-22 and IFNγ was detected in serum of mice receiving combination treatment when compared to mice receiving CART alone." (PMID 38730243, 2024). "The HFD increased immune suppressive MDSC in the blood, limiting the activation of tumor-reactive CD8+ T cells, and the HFD-induced tumor microenvironment showed elevated levels of IL-1β and IFNγ mRNA levels in 4T1 cell-bearing mice." (PMID 38999849, 2024). "Interleukin-12 (IL-12) emerges as a potent cytokine in fostering anti-tumor immunity by triggering interferon-gamma production in T and natural killer cells and changing macrophages to a tumoricidal phenotype." (PMID 38161192, 2024). "The therapeutic efficacy of TVQC correlated with significant induction of total and IFNg-producing tumor-antigen-specific CD8 T cells and NKDCs expressing granzyme B, IFNg or both in the tumor when compared to the untreated controls." (PMID 38400189, 2024). "Fifth, MH-induced improvement in anti-tumor immune responses was also evident when used in a therapeutic regimen and was completely dependent on IFNγ." (PMID 38444857, 2024). "In contrast, CD8+ T cells can induce tumor ferroptosis via lipid peroxide accumulation triggered by CD8+ T cells-secreted IFNγ to increase STAT1 and suppress cystine/glutamate antiporter system Xc in B16 beard mouse model." (PMID 38915413, 2024). "CD8+ T cells within the tumor environment can stimulate ferroptosis in tumor cells through the release of IFNγ, whereas lymphocytes protect metastasizing melanoma cells from ferroptosis." (PMID 38594504, 2024). "Using a mouse ID8-derived HGSC syngeneic model with IFNγ-inducible PD-L1 expression, BA treatments significantly reduced ascites development and tumour burden." (PMID 38622286, 2024). "Further investigation revealed that IFNγ selectively altered NAF+/β-catenin signaling in HPD-prone tumor models, confirming the key role of T cells in this mechanism." (PMID 38903504, 2024). "Previous studies demonstrated that Ras–MAPK activity can suppress the expression of MHC-I and MHC-II induced by IFNγ, and tumor cells can circumvent antigen presentation pathways by activating the MAPK pathway." (PMID 38600469, 2024). "By contrast, neutralization of IFNγ fully rescued tumor growth, while depletion of TAMs using a colony-stimulating factor 1 receptor (CSF1R) antibody partly rescued tumor growth." (PMID 37996514, 2024). "Lycopene has been shown to enhance the impact of PD-1 mAb therapy, resulting in increased tumor cell death, elevated production of anti-tumor cytokines (IL-2, IFNγ), and a higher CD4+/CD8+ ratio in the spleen." (PMID 38426097, 2024). "Drivers of ICB resistance include tumor antigen processing/presentation machinery (APM) and IFNγ signaling mutations." (PMID 38427670, 2024). "In the majority of patients, the progressive tumor lesion contained higher CD8+ T cell counts/mm2 and interferon-gamma (IFNγ) signature level, but similar tumor PD-L1 expression." (PMID 38280045, 2024). "By contrast, hypoxia suppresses the anti-tumor ability of these cells via HIF-1α down-regulation of IFNγ and NKG2D." (PMID 38816652, 2024). "For example, IL-12 signaling facilitates CAR-T cell-mediated IFNγ production, which is necessary for tumor cell killing, and intratumoral IL-12 delivery enhances CAR-T cell immunotherapy in preclinical models of glioblastoma." (PMID 39134804, 2024).
tumor (continued). "This study builds upon this foundation by investigating the relationship between PDL1 expression on tumor cells, IL-12 production, and IFNγ secretion by the PD1-Syn-IL-12-NK cells in a co-culture media." (PMID 38666913, 2024). "The impairment in NK cells has been correlated to the decrease in the anti-tumor immune response due to a decrease in cytotoxicity and interferon-gamma (IFN-gamma) production, accompanied by an increase in the suppressive Treg cells." (PMID 39906666, 2024). "The study showed that TILs demonstrated tumor-specific reactivity through a IFNγ release assay in 51 samples." (PMID 38279265, 2024). "As a result, without the addition of AH1 peptide, a few spots indicative of IFNγ production were observed in mice with complete tumor elimination, in addition the addition of AH1 significantly increased the number of spots." (PMID 39054418, 2024). "Analysis of the immune response in tumour-draining lymph nodes showed that the percentage of CD4+IFNγ+ cells was significantly higher in anti-IL-33 treated mice." (PMID 38662248, 2024). "Upon tumor antigen recognition by T cells, prolonged IFNγ production by T cells increases the expression of PD-L1 on tumor cells and tumor-associated macrophages." (PMID 39458207, 2024). "Small RNA sequencing was used to identify differentially expressed miRNA during TAM generation and following LPS/IFNγ stimulation to induce an anti-tumour phenotype." (PMID 39763667, 2024). "Treatment delayed tumor growth, while also inhibiting lung metastasis, reducing splenomegaly, increasing activated IFNγ+ CD4+ and CD8+ splenocytes, and increasing tumor infiltrating CD8+ T cells." (PMID 38803496, 2024). "IRF2 also regulated GADD45G, which has been reported to enhance IFNG production and anti-tumor immune effects." (PMID 39090334, 2024). "In response to this inflammation, immune cells, such as tumor-infiltrating lymphocytes (TILs), secrete cytokines such as interferon-gamma (IFN-gamma)." (PMID 38790938, 2024). "Anti-CTLA-4 Ab treatment resulted in recruitment of interferon-gamma (IFN-g)-producing CD4+ T cells, called T-helper 1 (Th1), into tumors, and neutralization of IFN-g abrogated the anti-tumor effects." (PMID 39106430, 2024). "Prolonged immunotherapy can elevate PD-1 expression in CD4+ and CD8+ T cells, leading to reduced infiltration of these cells into the tumor and decreased levels of activation markers such as IFNγ, TNFα, and granzyme B." (PMID 38927907, 2024). "Tumor cell-intrinsic interferon-gamma (IFN-γ) signaling is particularly important in anti-tumor immunity." (PMID 38829686, 2024). "IFNγ is a cytokine that not only exerts direct anti-tumor effects, but also plays a crucial role in subsequent adaptive immune responses." (PMID 38637557, 2024). "Blocking GPNMB by antibodies restores the integrity of T cells, attenuates tumor growth, and increases interferon-gamma levels in the tumor microenvironment." (PMID 38822058, 2024). "We also observed that the numbers of tumor-infiltrating granzyme B- or interferon gamma (IFNγ)-producing CD8+ T cells were significantly greater in TOFA-Th9 cells than in untreated Th9 cells." (PMID 39187636, 2024). "In contrast, at all E:T ratios tested, fewer Lysate‐derived T cells for the same tumor cell lines secreted IFNγ in response to target cells, suggesting that these T cell products are less specific and responsive to the target cells." (PMID 38818122, 2024). "Preclinical studies reported that the Semliki Forest virus can encode IL-12 (SFV‐IL12), and this type of virotherapy can induce PD‐L1 expression on tumor cells in an IFNγ‐mediated fashion." (PMID 39015563, 2024). "Understanding the contexts in which tumor-intrinsic IFNγ signaling promotes or impedes antitumor immunity will be important when assessing combination strategies targeting this pathway." (PMID 38635884, 2024). "Our results demonstrated the reversal of Granzyme B and IFNγ inhibition by CD8 + T cells from tumor tissues following TIGIT blockade." (PMID 38216949, 2024).
tumor (continued). "Through both direct induction of tumor cell death and indirect stimulation of myeloid phagocytosis in the tumor microenvironment, interferon gamma (IFNγ) emerges as a key player in bolstering cytotoxicity against solid tumors." (PMID 38893085, 2024). "TAA-specific CD8+ T cell frequency, characterized by IFNγ+ and/or 4-1BB+, was inversely correlated with both clinical progression (cStage) and tumor diameter on CT before treatment initiation." (PMID 38550601, 2024). "Our findings showed major changes occurring during the first 24 h culture period of PCTS, involving genes related to wound healing, extracellular matrix, hypoxia, and IFNγ-dependent pathways in both tumor types, as well as tumor-specific changes." (PMID 38744944, 2024). "In the TCGA BRCA dataset, similarly, the authors have demonstrated significant associations between lower expression of IFNG, CD40LG, and CXCR5 and larger tumor sizes or adjacent tissue invasion (p = 0.01, p = 0.03, and p = 0.01, respectively)." (PMID 39001456, 2024). "Specifically, an HSD induces NK cell-mediated tumor immunity by suppressing PD-1 expression while increasing IFNγ levels and the serum hippurate concentration." (PMID 38462638, 2024). "In contrast, the combination of C‐C motif chemokine ligand 2 (CCL2) and interferon gamma (IFN‐g) can drive an anti‐tumour phenotype in PDAC myeloid cells, and this is particularly important in the presence of CD40 agonist treatment." (PMID 38426634, 2024). "In the light of these data, the authors suggest a model where tumor-specific accumulation of the edited Tregs that secrete IFNγ, results in elevated levels of IFNγ in the TME." (PMID 38698860, 2024). "As a major inflammatory cytokine, IFNγ plays a key role in shaping immune response induction, tumor immunosurveillance, and the maintenance of normal tissue homeostasis." (PMID 38385075, 2024). "Conversely, blockade of interleukin-10 signaling preferentially enhanced the capacity of CD8+ T cells to secrete Interferon gamma when being cocultured with CBM588-primed lamina propria mononuclear cells of tumor-bearing mice." (PMID 38385162, 2024). "We previously found LXR agonist was able to promote the expression and secretion of IFNγ, and exert the anti-tumor efficiency." (PMID 38630355, 2024). "Among the Th cells, Th1 supports anti-tumor immunity by secreting IFNγ, while regulatory T cells (Treg), can suppress immune responses and promote tumor tolerance." (PMID 39684307, 2024). "Since the STAT1-IFITM3 feedback loop depends on IFNγ, our research also provides innovative sights of targeting Treg perturbation to regulate anti-tumor immunity in the IFNγ-enriched tumor microenvironment." (PMID 38167862, 2024). "It appears that the intrinsic effects of the IRF1 protein on carcinogenesis and tumor growth are as ambivalent as the known functions of the IFNγ signaling pathway itself." (PMID 38396830, 2024). "Successful activation of immune therapy recruits CD8 T cells to the tumor site, enhancing tumor cell ferroptosis via IFNγ-related pathways, representing a significant advancement in efficient tumor eradication strategies." (PMID 39209834, 2024). "For example, CD8+ T cells suppress the expression of SLC7A11 and SLC3A2 in tumor cells via IFNγ release, increasing tumor cell sensitivity to ferroptosis." (PMID 39273090, 2024). "It has been shown that the shift in the accumulation of intratumoral γδ T cells from antitumor IFNγ‐producing ones toward the protumor immunosuppressive IL‐17‐secreting γδ T cells increases through the stages of tumor progression." (PMID 38703051, 2024). "While endogenous IFNγ signaling is clearly important for immune surveillance, high-dose administration of exogenous IFNγ strongly stimulates PD-L1 expression in the tumor microenvironment, and hampers therapy with agents that enforce ICB." (PMID 38962090, 2024).
tumor (continued). "The increase in CD8+ GrzB+ T cells, CD8+ IFNγ+ T cells and CD4+ IFNγ+ T cells under combination therapy indicated activation of T cell-mediated tumor toxicity." (PMID 38589867, 2024). "IFNγ can contribute to increased anti-tumor activity of CD8+ T cell response and the DNA damage response induced by NOX4 can lead to activation of cell cycle checkpoints that arrest proliferation and/or induce apoptosis of tumor cells." (PMID 39588838, 2024). "To demonstrate the functional impact of the observed IFNγ signature, we treated mice bearing MEK1‐low and MEK1‐hi 9609 tumours with control IgG or antibodies blocking IFNγ." (PMID 39330930, 2024). "For instance, we previously determined that IFNγ-dependent angiostasis is a key mechanism in T cell-mediated anti-tumor immunity." (PMID 39033271, 2024). "There is an exciting piece of evidence suggesting that increased infiltration of interferon gamma (IFNγ)-producing activated T cells in the tumor tissues also triggers the upregulation of PD-L1 in the cancer cells." (PMID 38434765, 2024). "NK cells are one of the primary producers of IFNγ, which has been shown to significantly enhance the cytotoxic activity and tumor infiltration of NK cells." (PMID 39294470, 2024). "On the contrary, the recruitment of CXCR3-expressing T cells has been associated with an improved antitumor immunity, and IFNG and CXCL10 have been shown to inhibit the growth of MM cells, pointing towards a potential role in immune-mediated tumor control." (PMID 39613747, 2024). "In a model of tumor growth under chronic stress, Fx therapy suppressed the kynurenine pathway, enhanced Ser/5-HT levels and cellular immunity involving CD8+ T-cells and IFNγ, and improved tumor control." (PMID 38776344, 2024). "A tumor’s capacity to react to interferon-gamma (IFN-γ), a cytokine essential for immune-mediated tumor elimination, can be hindered by mutations in the JAK1/2 gene, for instance." (PMID 39273605, 2024). "NK cells in sMICB-expressing tumors had a significantly reduced response to PMA/I stimulation as measured by IFNγ expression (p < 0.05 for all models), one of the key effector molecules for NK cell mediating anti-tumor immunity." (PMID 38255301, 2024). "CD4+ T cells secrete different tumouricidal cytokines, such as interferon-γ (IFNγ) and TNFα to support CTLs in the disruption of primary tumour cells." (PMID 39000359, 2024). "A positive correlation between the PDL1 levels on tumor cells, IL-12 production by engineered NK cells, and increased IFNγ secretion highlighted the immunostimulatory potential of this construct against the PDL1-expressing tumor cells." (PMID 38666913, 2024). "For both subsets of γδ TRM, ZNF683 (Hobit), CD81, CD82, and IFNG expression is higher in the tumor compared to normal tissue." (PMID 39454432, 2024). "Consistent with the regulon profile, tumor-reactive T cells exhibited higher expression of pro-inflammatory effector molecules such as IFNG, TNF, and PRF1 and lower expression of genes like LBT, CD27, and CD28." (PMID 39243082, 2024). "IL-12 secreting CAR T cells highlighted their tumor killing effect by reducing Treg activity and empowering IFNγ secretion." (PMID 39835140, 2024). "IL-6 blockade sensitized EGFR-mutant GEMM tumors to PD-1 inhibitors by increasing tumor-infiltrating IFNγ+ CD8+ T cells." (PMID 39015563, 2024). "It is worth noting that induction of IDO1 expression in response to interferon-gamma (IFNγ), an effector molecule of CTLs in the tumor, is recognized as one of the tumor’s mechanisms of evading immune surveillance." (PMID 39346737, 2024). "This cytokine impedes CTL effector differentiation and gene expression, including IFNγ and perforin expression, leading to anti-PD-L1 therapy resistance in preclinical tumor model." (PMID 38715072, 2024). "We found that the JK10 CAR had a stronger IFNγ and TNFα response, as measured in overnight co-culture assays with tumor target cells." (PMID 38203757, 2024).
tumor (continued). "NK cells, crucial for tumor surveillance and immunotherapy, exert cytotoxic effects on tumor cells through perforin, granzyme, and IFNγ release." (PMID 39273090, 2024). "In the PDA7940b tumor model, significantly more IL-18, IFNγ, and IL-2 was detected in mouse serum from the combination treatment group comparted to CART alone." (PMID 38730243, 2024). "In this set of tumor cultures, the levels of secreted IFNγ were below the lower limit of quantification." (PMID 38892347, 2024). "This suggests that IL‐2‐Fc treatment causes a stronger initial antitumor immune response than ICK due to far better elimination of Tregs, but ICK appears to maintain this response better in the long term mainly by increased IFNγ+CD8+ T cell tumor infiltration." (PMID 38317590, 2024). "With regard to acquired resistance, it is informative that CRISPR screens of tumor cells evading either PD1 blockade or T cell co-culture converge on inactivation of two pathways: interferon-gamma signaling and MHC-I antigen presentation." (PMID 38594286, 2024). "Blocking the inflammatory cytokine IFNγ or directly depleting STAT1-IFITM3 axis phenocopies the restored suppressive function of tumor-infiltrating Tregs in the tumor model." (PMID 38167862, 2024). "Following radiation, the release of damage-associated molecular patterns (DAMPs) and IFNγ occurs, promoting the migration and infiltration of CAR-T cells into the tumor." (PMID 39335671, 2024). "Interferon gamma (IFNγ) released by CD8+T cells in the tumor microenvironment restrains cystine uptake, and tumor cells deficient in cystine have difficulty in resisting lipid peroxidation and thus promote ferroptosis." (PMID 38575922, 2024). "As expected, tumor development in the control—PBS-injected B16F10 tumor-bearing animals—resulted in higher serum levels of IFNγ in the end-points compared to the Hcs-treated mice under all regimens of administration." (PMID 38786612, 2024). "In pre-clinical mouse models, γδ T cells have been shown to be a critical source of IFNγ during tumor surveillance." (PMID 38321065, 2024). "In contrast, EV‐MEK1 acts as a tumour suppressor by stimulating anti‐tumour immunity via a mechanism likely involving macrophages, IFNγ, and adaptive immunity." (PMID 39330930, 2024). "B7-H3-targeted ADCC mAb functions by linking NK cells to B7-H3-expressing tumor cells that are subject to increased IFNγ paracrine signaling from the NK cells." (PMID 38893085, 2024). "It has been shown that IFNγ, derived from TILs, induces PD-L1 expression on tumor cells and/or in TME." (PMID 39469633, 2024). "Cbx3 KO increased CRC tumor chemosensitivity under IFNγ stimulation is also confirmed with MC38 syngeneic mouse tumor model." (PMID 38684864, 2024). "Enzyme‐linked immunosorbent assays demonstrated that the AISI‐pLuxI‐htrA strain effectively increased the key antitumor cytokines level, including IFNγ and TNFα, within the tumor and peripheral blood compared to those in the AISI‐NC strain." (PMID 39058336, 2024). "T cells developed against all tumor types significantly (p < 0.05 compared to actin) secreted IFNγ in response to exposure to target cells in an E:T ratio‐dependent manner." (PMID 38818122, 2024). "At the time‐point used (13 days), only a minimal impact was observed on tumour levels of IFNγ following treatment with ADC‐159 alone." (PMID 38602256, 2024). "GSEA showed that mT4 macrophages were enriched in TGFβ and TNFα signaling via NF-kB pathways, while B16F10 macrophages were enriched in interferon-gamma and alpha response pathways, indicating their opposing functions in the tumor." (PMID 38987547, 2024). "On the other hand, the optimal induction of NOS2 and COX2 in murine and human tumor cells requires IFNγ, and its combination with TNF-⍺ and IL-1β was more effective than with LPS." (PMID 38892290, 2024). "At an E:T ratio of 1:1, 167 to 2238 T cells secreted IFNγ in response to target cells, depending on the tumor type." (PMID 38818122, 2024).